RNU6-591P (RNA, U6 small nuclear 591, pseudogene)
Gene: Small nuclear RNA gene on chromosome X (39,081,180 to 39,081,285, reverse strand). Ensembl gene ENSG00000207122.
Homologues: Orthologues: chimpanzee U6 (100% identical), macaque U6 (95% identical), pig U6 (81% identical), dog U6 (76% identical), pig U6 (76% identical), pig U6 (70% identical). Paralogues in human: RNU6-1060P (87% identical), RNU6-1251P (87% identical), RNU6-1011P (86% identical), RNU6-10P (86% identical), RNU6-12P (86% identical), RNU6-13P (86% identical), RNU6-16P (86% identical), RNU6-32P (86% identical), RNU6-33P (86% identical), RNU6-41P (86% identical), RNU6-592P (86% identical), RNU6-1 (85% identical), and 1285 more.